LINC02701 (long independently transcribed non-coding RNA 2701)
Gene: Long non-coding RNA gene on chromosome 11 (68,870,664 to 68,874,542, forward strand). Ensembl gene ENSG00000250508.
Diseases named in the same sentence as LINC02701 in open-access papers:
LINC02701 is named in the same sentence as 2 diseases in open-access papers, as found by Europe PMC text mining. Sharing a sentence is not in itself a finding about the gene and the disease. The quoted sentences say what the papers report.
Parkinson disease (1 paper, 2022). A progressive degenerative disorder of the central nervous system characterized by loss of dopamine producing neurons in the substantia nigra and the presence of Lewy bodies in the substantia nigra and locus coeruleus. "LINC02701 has not been previously reported to be associated with cancer, but LINC02701 mRNA expression was significantly raised in patients with Parkinson’s disease compared to normal controls." (PMID 35454778, 2022).
LINC02701 also shares sentences with these, for which no sentence is quoted: cancer (1 paper).